NAT10 (N-acetyltransferase 10)
Diseases named in the same sentence as NAT10 in open-access papers (continued):
Sharing a sentence is not in itself a finding about the gene and the disease.
Hypertension (2 papers, 2023 to 2025). The presence of chronic increased pressure in the systemic arterial system. "Thus, our data suggest that NAT10-induced targeted ac4C acetylation of mRNAs may be associated with the MAPK pathway in hypertension." (PMID 41254488, 2025). "The present study revealed the molecular mechanism by which NAT10-mediated ac4C acetylation affects mRNA-related endothelial function in hypertension." (PMID 41254488, 2025). "Collectively, our findings illustrated the role of the NAT10-AdipoR1 axis in hypertension, with a specific focus on mRNA ac4C acetylation-mediated regulation of mitochondrial biogenesis and function in Ang II-treated ECs." (PMID 41254488, 2025). "ac4C-RIP-seq and RNA-seq were carried out to detect the effect of NAT10-induced ac4C acetylation on hypertension." (PMID 41254488, 2025). "Through molecular and rescue assays, we determined that NAT10 inhibits EndMT in hypertension through AdipoR1 mRNA ac4C acetylation, which is partly due to protection of endothelial function." (PMID 41254488, 2025). "Taken together, these results suggest that NAT10 induction mediates ac4C acetylation in complex hypertension progression." (PMID 41254488, 2025). "The current findings highlighted that the NAT10-AdipoR1-PGC-1α axis may be a therapeutic target for hypertension treatment." (PMID 41254488, 2025). "An in vivo assay was conducted to assess the effect of NAT10 on hypertension development." (PMID 41254488, 2025). "Taken together, our data highlighted that increasing NAT10-induced ac4C acetylation might be an effective therapeutic approach for hypertension." (PMID 41254488, 2025). "This phenomenon might contribute to the function of NAT10 in hypertension." (PMID 41254488, 2025). "Thus, increased NAT10 expression in EC may serve as an initial adaptive response to hypertension." (PMID 41254488, 2025). "Moreover, NAT10 may also mediate hypertension through the regulation of VSMC function." (PMID 41254488, 2025).
inflammatory bowel disease (2 papers, 2025). A spectrum of small and large bowel inflammatory diseases of unknown etiology. "Our findings also suggest that targeted modulation of NAT10 may play a crucial role in the treatment of IgA nephropathy or inflammatory bowel disease (IBD)." (PMID 40615576, 2025). "N4-acetylcytidine (ac4C), the only known acetylation modification in RNA catalyzed by N-acetyltransferase 10 (NAT10), is known to enhance mRNA stability and translation, yet its role in inflammatory bowel disease (IBD) remains unclear." (PMID 40038243, 2025).
ischemia (2 papers, 2024 to 2025). A hypoperfusion of the BLOOD through an organ or tissue caused by a PATHOLOGIC CONSTRICTION or obstruction of its BLOOD VESSELS, or an absence of BLOOD CIRCULATION. "Cardiac apoptosis-associated piRNA (HAAPIR) promotes cardiomyocyte apoptosis by recruiting N-acetyltransferase 10 (NAT10) to facilitate the acetylation of TFEC mRNA and thus is a key regulator of apoptosis in cardiomyocyte cells in response to ischemia and reperfusion injury." (PMID 38915084, 2024).
leukaemia (2 papers, 2021 to 2023). "Interestingly, lower expression of NAT10 was found in one leukemia dataset." (PMID 34094911, 2021).
metastasis (2 papers, 2023 to 2025). The spread or migration of cancer cells from one part of the body (where they first appeared) to another. "In our study, we found that patients with lymphatic metastasis had higher NAT10 expression levels than those without lymphatic metastasis, and we speculated that NAT10 may promote lymphatic metastasis in HNSCC." (PMID 37914704, 2023).
oral squamous cell carcinoma (2 papers, 2025). "In oral squamous cell carcinoma, lentivirus-mediated NAT10 knockdown markedly suppressed cell migration and invasion." (PMID 40588654, 2025). "Notably, NAT10-mediated RNA acetylation also plays a role in CESC and oral squamous cell carcinoma (OSCC) progression." (PMID 41316475, 2025).
premature aging syndrome (2 papers, 2017 to 2019). Changes in the organism associated with senescence, occurring at an accelerated rate. "Besides, it has been indicated that NAT10 involves in affecting the nuclear architecture for the recent work found that NAT10 is the target of the small molecule “Remodelin” which can be used to treat premature aging syndromes by correcting nuclear architecture." (PMID 28859621, 2017).
premature ovarian failure (2 papers, 2023 to 2025). "Consistent with the high expression levels of Nat10 in the female germline, pre-meiotic ablation of Nat10 caused apparent meiotic arrest at the pachytene stage, resulting in premature ovarian failure and female infertility in adults." (PMID 37349316, 2023). "These tubules were devoid of oocytes in the center, presumably owing to the quick degeneration of the Nat10-null oocytes, reminiscent of premature ovarian failure (POF)." (PMID 37349316, 2023). "In summary, pre-meiotic ablation of Nat10 in the female gonad led to female infertility due to follicular arrest at the primary follicle stage and premature ovarian failure." (PMID 37349316, 2023). "Loss of NAT10 before meiosis resulted in the cessation of follicle development at the primary stage and premature ovarian failure (POF), and in vitro ablation of NAT10 in GV oocytes impaired meiotic progression from GV to MII stage." (PMID 39969189, 2025).
rectal adenocarcinoma (2 papers, 2024 to 2025). "We first analyzed NAT10 expression at the mRNA level in colon adenocarcinoma and rectal adenocarcinoma samples and paired non-malignant tissues based on GEPIA data." (PMID 39905540, 2025).
Arthritis (1 paper, 2025). Inflammation of a joint. "Thus, macrophage training activated the IL‐1β/NAT10/ac4C/FSP1 axis to inhibit ferroptosis of arthritis synovial FLS, indicating a causal link between trained immunity and ferroptotic resistance that contributes to the worsening of inflammatory arthritis." (PMID 41255239, 2025). "In a collagen‐induced arthritis model, trained macrophages intensify disease severity and confer ferroptosis resistance in synovial cells via IL‐1β/NAT10‐mediated FSP1 mRNA modification." (PMID 41255239, 2025). "Thus, we inferred that macrophage training induced IL‐1β/NAT10‐mediated ac4C modification on FSP1 mRNA, thereby protecting arthritis synovial FLS from ferroptosis." (PMID 41255239, 2025). "In arthritis progression, trained macrophages reduce fibroblast‐like synoviocytes’ (FLS) lipid peroxidation, lessening sensitivity to iFSP1‐induced ferroptosis through interleukin‐1 beta (IL‐1β)/N‐acetyltransferase 10 (NAT10)/ferroptosis suppressor protein 1 (FSP1) mRNA ac4C modification." (PMID 41255239, 2025).
breast tumors (1 paper, 2025). "In contrast, we also found that the NAT function of NAT10 is required for breast tumor growth and metastasis in mice." (PMID 40138393, 2025).
cervical tumor (1 paper, 2024). "In this study, we found that circMAST1 inhibited cervical tumor growth and metastasis by regulating the NAT10/YAP axis." (PMID 38331765, 2024).
Crohn disease (1 paper, 2025). A gastrointestinal disorder characterized by chronic inflammation involving all layers of the intestinal wall, noncaseating granulomas affecting the intestinal wall and regional lymph nodes, and transmural fibrosis. "Moreover, in patients with Crohn’s disease (CD), NAT10 expression in colonic B cells exhibited a strong negative correlation with disease severity index." (PMID 40615576, 2025).
endotoxemia (1 paper, 2025). "Using bone marrow-derived macrophages and an endotoxemia mouse model, we found that NAT10 is significantly upregulated in response to lipopolysaccharide (LPS) due to the deubiquitinating enzyme USP39, which stabilizes the NAT10 protein." (PMID 40593466, 2025). "Our findings provide further insight into the roles of Ets2 and NAT10 in macrophage function, revealing a post-transcriptional mechanism that regulates the inflammatory response in endotoxemia." (PMID 40593466, 2025). "Having demonstrated that NAT10 inhibition prevents cardiac dysfunction in an endotoxemia mouse model, we investigated the therapeutic potential of remodelin in endotoxemia treatment." (PMID 40593466, 2025).
esophageal tumor (1 paper, 2025). "Lastly, NAT10 serves as a substrate for Khib modification, where K823 modification of NAT10 enhances its association with USP39, promoting NOTCH3 mRNA stabilization and consequently fostering esophageal tumor dissemination." (PMID 40588654, 2025).
fibrosis (1 paper, 2024). the formation of excess fibrous connective tissue in an organ or tissue in a reparative or reactive process. "In the cardiac fibrosis tissues of chronic myocardial infarction mice and cultured cardiac fibroblasts (CFs) in response to TGF‐β1 treatment, there was an elevation in the levels of NAT10 expression." (PMID 39482983, 2024).
focal segmental glomerulosclerosis (1 paper, 2025). A renal disorder characterized by sclerotic lesions in the glomeruli. "The role of NAT10 was established in an ADR-induced nephropathy model, which simulates the pathological type of focal segmental glomerulosclerosis." (PMID 40108127, 2025).
Helicobacter pylori (1 paper, 2023).
hemorrhage (1 paper, 2025). Loss of blood from the vascular compartment to the exterior or into nonvascular body space as a result of rupture or severance of the blood vessels. "Despite this, there are several mechanisms via which NAT10 might exacerbate thalamic pain caused by hemorrhage., which deserve further study, like protein–protein interaction networks." (PMID 39271624, 2025).
Hepatic steatosis (1 paper, 2025). Steatosis is a term used to denote lipid accumulation within hepatocytes. "Furthermore, in metabolic dysfunction-associated steatotic liver disease (MASLD), silencing NAT10 markedly reduces hepatic lipogenesis markers and improves hepatic steatosis." (PMID 40588654, 2025). "Research has discovered that NAT10 could exacerbate high-fat-diet-induced liver steatosis, whereas knockout of NAT10 could protect from diet-induced hepatic steatosis and steatohepatitis." (PMID 40588654, 2025).
hepatoblastoma (1 paper, 2025). Hepatoblastoma (HB) is a malignant hepatic tumor and is the most common pediatric liver cancer. "To elucidate potential upstream signaling pathways regulating NAT10 expression, we treated hepatoblastoma (HB) cells with various small-molecule inhibitors and assessed NAT10 expression via qRT-PCR." (PMID 40303290, 2025). "To investigate NAT10 expression in hepatoblastoma (HB) tissues, we analyzed data from the TCGA and GSE131329 databases." (PMID 40303290, 2025). "Overall, our findings indicates that NAT10 is a promising therapeutic target for conquering resistance in hepatoblastoma treatment." (PMID 40303290, 2025). "Furthermore, we discovered that the NAT10 inhibitor Remodelin effectively inhibited the malignant progression of hepatoblastoma." (PMID 40303290, 2025). "In this study, we demonstrated that NAT10 could promote the malignant progression of hepatoblastoma both in vitro and in vivo, mediating ac4C modification to upregulate G6PD expression and activate PPP." (PMID 40303290, 2025). "Additionally, NAT10 was primarily positively regulated by the upstream YAP1 signaling pathway and activated PPP, thereby influencing the metabolic reprogramming in hepatoblastoma, further promoting cancer cell proliferation, invasion, and metastasis." (PMID 40303290, 2025).
IgA nephropathy (1 paper, 2025). "Our findings highlight the potential of NAT10 as a therapeutic target for modulating mucosal immunity, particularly in the context of IgA-related pathologies such as IgA nephropathy and IBD." (PMID 40615576, 2025).
latent infection (1 paper, 2024). "We and others have previously found that lactate accumulates not only during KSHV latent infection, but also in the medium of iSLK-KSHV cells after doxycycline induction, indicating that lactate-driven lysine lactylation may be involved in NAT10-mediated viral reactivation." (PMID 38879723, 2024).
liver fibrosis (1 paper, 2025). "Sirius Red staining in the DEN/CCL4‐induced model further revealed that NAT10‐2023 significantly alleviated liver fibrosis progression." (PMID 41476650, 2025). "Sirius Red staining in the DEN/CCL4‐induced model showed that NAT10 knockdown effectively suppressed liver fibrosis progression." (PMID 41476650, 2025).
male infertility (1 paper, 2022). The inability of the male to effect fertilization of an ovum after a specified period of unprotected intercourse. "With germ cell-specific inactivation of Nat10, both Mettl3 and Mettl14 can cause defects in spermatogenesis and male infertility." (PMID 35801907, 2022).
metastatic tumors (1 paper, 2025). "Further studies have shown that the expression of NAT10 in metastatic tumors was higher than that in non-metastatic tumors." (PMID 41189569, 2025).
Nephropathy (1 paper, 2025). A nonspecific term referring to disease or damage of the kidneys. "In this study, TLR2 expression was increased in the ADR-induced nephropathy model, while Remodelin and NAT10 siRNA treatment reduced TLR2 levels." (PMID 40108127, 2025). "In this study, elevated NAT10 expression was observed in an ADR-induced nephropathy model." (PMID 40108127, 2025). "In summary, this study revealed the crucial role of NAT10 in regulating DNA damage and senescence-related genes in the ADR-induced nephropathy model." (PMID 40108127, 2025). "Therefore, this study aims to investigate the mechanisms by which NAT10 influences senescence and damage in an adriamycin (ADR)-induced nephropathy model." (PMID 40108127, 2025).
peripheral nerve injury (1 paper, 2025). Injury to a peripheral nerve. "Upregulated NAT10 levels were also observed in mice with peripheral nerve injury, which is crucial in regulating the development of neuropathic pain." (PMID 40119353, 2025).
prostate adenocarcinoma (1 paper, 2024). "Survival analysis using The Cancer Genome Atlas-Prostate Adenocarcinoma (TCGA-PRAD) data indicated a significant inverse correlation between NAT10 expression and progression-free survival, with higher NAT10 levels linked to poorer outcomes." (PMID 39648231, 2024).
prostate tumors (1 paper, 2024). "The results showed that the knockdown of NAT10 effectively inhibited the growth of prostate tumors, which was reflected by a significant reduction in the volume and weight of the tumors compared to the control group." (PMID 38922788, 2024).
pulmonary fibrosis (1 paper, 2025). Chronic progressive interstitial lung disorder characterized by the replacement of the lung tissue by connective tissue, leading to progressive dyspnea, respiratory failure, or right heart failure. "In pulmonary fibrosis, NAT10 accelerates disease progression by stabilizing transforming growth factor beta 1 (TGFB1) mRNA in an ac4C-dependent manner, promoting epithelial-to-mesenchymal transition (EMT) and fibrosis upon exposure to ambient particulate matter." (PMID 40588654, 2025).
pulpitis (1 paper, 2025). Inflammation of the dental pulp. "By knocking down NAT10 and using its inhibitor Remodelin, this study investigated the regulatory effect and potential mechanism of ac4C modification mediated by NAT10 in the regulation of pulpitis." (PMID 40362562, 2025). "In the present study, increased NAT10 expression was observed in pulp tissues from patients with pulpitis, which is consistent with the expression of NAT10 in LPS-stimulated hDPSCs." (PMID 40362562, 2025). "In this study, elevated NAT10 expression was observed in pulpitis tissues and LPS-stimulated hDPSCs." (PMID 40362562, 2025). "The results showed that NAT10 expression was elevated in pulpitis tissues compared to healthy pulp tissues, which was in line with the expression of NAT10 mRNA." (PMID 40362562, 2025). "Remodelin, a specific inhibitor of NAT10, was evaluated for its therapeutic potential in the inflammatory model of hDPSCs in vitro and the pulpitis model of rats in vivo." (PMID 40362562, 2025). "Similar results were obtained when NAT10 expression was detected in rat dental pulp from the control group and pulpitis group by immunofluorescence." (PMID 40362562, 2025). "To further investigate the therapeutic potential of Remodelin, a specific NAT10 inhibitor, we applied it to a LPS-stimulated DPSC and pulpitis model of rats." (PMID 40362562, 2025).
tongue cancer (1 paper, 2023). A malignant neoplasm affecting the tongue. "Specimens of normal, tongue hyperplasia, and tongue carcinoma mice after 4-NQO withdrawal were obtained to detect the expression levels of NAT10 and GLMP using HE staining and western blotting." (PMID 37914704, 2023).
ulcerative colitis (1 paper, 2025). An inflammatory bowel disease involving the mucosal surface of the large intestine and rectum. "In this study, we discovered that Nat10 expression correlates with inflammatory and apoptotic pathways in human ulcerative colitis CD4+ T cells." (PMID 40038243, 2025).